EMC4 (ER membrane protein complex subunit 4)
Description:
Part of the endoplasmic reticulum membrane protein complex (EMC) that enables the energy-independent insertion into endoplasmic reticulum membranes of newly synthesized membrane proteins. Preferentially accommodates proteins with transmembrane domains that are weakly hydrophobic or contain destabilizing features such as charged and aromatic residues. Involved in the cotranslational insertion of multi-pass membrane proteins in which stop-transfer membrane-anchor sequences become ER membrane spanning helices. It is also required for the post-translational insertion of tail-anchored/TA proteins in endoplasmic reticulum membranes. By mediating the proper cotranslational insertion of N-terminal transmembrane domains in an N-exo topology, with translocated N-terminus in the lumen of the ER, controls the topology of multi-pass membrane proteins like the G protein-coupled receptors. By regulating the insertion of various proteins in membranes, it is indirectly involved in many cellular processes (Probable).
Synonyms: TMEM85; PIG17; FLJ90746; MGC24415
Tractability: Small molecule: a structure with a bound ligand is known. Antibody: UniProt predicts a signal peptide or a membrane-spanning region. PROTAC: ubiquitination databases record sites on it; its protein half-life has been measured.
Gene: Protein-coding gene on chromosome 15 (34,225,013 to 34,230,161, forward strand). Ensembl gene ENSG00000128463.
Subcellular location: Endoplasmic reticulum membrane
Pathways (Reactome):
Disease: Dengue Virus Attachment and Entry
Gene Ontology:
Molecular function: membrane insertase activity; protein binding
Biological process: protein insertion into ER membrane by stop-transfer membrane-anchor sequence; tail-anchored membrane protein insertion into ER membrane
Cellular component: EMC complex; endoplasmic reticulum membrane; membrane
Genetic constraint (gnomAD): Loss-of-function variants: 9 observed, 22.22 expected, observed/expected ratio (o/e) 0.41, 90% interval 0.24 to 0.71. The upper end of that interval is the gene's LOEUF score, 0.71, which puts it in group 2 of 6, group 1 being the genes least tolerant of losing a copy. Missense variants: 160 observed, 228.57 expected, observed/expected ratio (o/e) 0.7, 90% interval 0.62 to 0.8. Synonymous variants: 79 observed, 78.01 expected, observed/expected ratio (o/e) 1.01, 90% interval 0.84 to 1.22.
Homologues: Orthologues: chimpanzee EMC4 (100% identical), macaque EMC4 (100% identical), guinea pig EMC4 (99% identical), mouse Emc4 (99% identical), rat Emc4 (99% identical), pig EMC4 (99% identical), rabbit EMC4 (99% identical), dog EMC4 (98% identical), tropical clawed frog emc4 (84% identical), Drosophila melanogaster EMC4 (48% identical), Caenorhabditis elegans perm-3 (37% identical), zebrafish EMC4 (28% identical), and 1 more.
Diseases named in the same sentence as EMC4 in open-access papers:
EMC4 is named in the same sentence as 11 diseases in open-access papers, as found by Europe PMC text mining. Sharing a sentence is not in itself a finding about the gene and the disease. The quoted sentences say what the papers report.
virus infection (3 papers, 2016 to 2022). "To assess the functional consequence of deleting the LCR from EMC4 during SV40 entry, we asked if expression of FLAG-Δ50 EMC4 can restore the block in virus infection due to knockdown of EMC4." (PMID 32111841, 2020). "Using this approach, we found that whereas knockdown of EMC4 blocked SV40 infection, expressing EMC4-FLAG under the EMC4 knockdown condition fully restored virus infection." (PMID 32111841, 2020). "Because addition of PS to cells stimulated DENV-LE membrane fusion and virus infection, we hypothesized that EMC4-dependent stabilization of the LE-ER MCS mediates the efficient efflux of PS from the ER to the LE." (PMID 35834589, 2022). "Specifically, we found that a component of an endoplasmic reticulum protein complex called EMC4 supports fusion of the DENV and endosomal membranes—this event delivers the viral genome into the host cytosol to drive virus infection." (PMID 35834589, 2022). "In cells depleted of EMC4, whereas expression of FLAG-EMC4 restored virus infection (compare third to second bar), similar to EMC4-FLAG, expressing FLAG-Δ50 EMC4 did not (compare fourth to second bar)." (PMID 32111841, 2020). "In fact, our data suggest that other EMC subunits, particularly EMC3, EMC4, EMC5, EMC6, EMC7, and EMC10, may also exert roles in supporting virus infection." (PMID 28012275, 2016).
Flavivirus Infections (1 paper, 2019). Infections with viruses of the genus FLAVIVIRUS, family FLAVIVIRIDAE. "It is worthwhile noting that EMC4 depletion did not destabilise other subunits but did preclude maturation of SQS and other TMD-containing proteins, and also suppressed flavivirus infection, reflecting an important role in EMC functionality." (PMID 30578317, 2019).
multiple system atrophy (1 paper, 2026). Multiple system atrophy (MSA) is a neurodegenerative disorder characterized by autonomic failure (cardiovascular and/or urinary), parkinsonism, cerebellar impairment and corticospinal signs with a median survival of 6-9 years. "OXR1 activation preferentially modulated cellular reactions to fibrils derived from multiple system atrophy (MSA) patients, whereas EMC4 ablation broadly reduced pSyn129 across diverse αSyn polymorphs." (PMID 41911287, 2026).
infection (4 papers, 2019 to 2022). The state of being infected such as from the introduction of a foreign agent such as serum, vaccine, antigenic substance or organism. "(C) Ribosome Profiling (Ribo-seq) and RNA-seq were performed in DENV-infected WT and EMC4-KO HEK293FT cells 44 hr post-infection to measure changes in translation efficiency (TE)." (PMID 31516121, 2019). "(B) Ribosome Profiling (Ribo-seq) and RNA-seq were performed in DENV-infected WT and EMC4-KO HEK293FT cells 18 hr post-infection to measure changes in translation efficiency (TE)." (PMID 31516121, 2019). "(C) Immunoblot analysis of DENV proteins from infected WT and EMC4-KO HEK293FT cells at different timepoints post-infection (6/8/10/12 hr)." (PMID 31516121, 2019). "EMC4 KD also decreased infection of the related Zika virus (ZIKV)." (PMID 35834589, 2022). "Thus the N-terminal cytosolic domain of EMC4 that harbors a unique LCR essential for Rab7 binding is functionally important to promote ER-arrival of SV40 leading to productive infection." (PMID 32111841, 2020). "Interestingly, in EMC4 KO cells the RLuc signal produced by infection was above the CHX control at 1.5 and 2 hr pi, suggesting that the block imposed by lack of EMC4, although profound, is not absolute." (PMID 31273220, 2019). "We analyzed infection of DENV strains from two different serotypes in EMC4 KO cell lines." (PMID 31273220, 2019). "Together these results demonstrate that EMC4 plays a critical role in DENV (and likely other flavivirus) infection." (PMID 35834589, 2022). "Our data thus far suggest that EMC4 and EMC7 support LE-to-ER transport of SV40 in order to promote productive infection." (PMID 32111841, 2020). "Strikingly, we found that depletion of EMC4 or EMC7 blocked SV40 infection because the virus cannot reach the ER from the LE, a critical infection step; under this compromised condition, SV40 is trapped in the LE as expected." (PMID 32111841, 2020). "In sum, these findings suggest that EMC4 and EMC7 function as molecular tethers, juxtaposing the ER to the LE to enable efficient transport of SV40 from the LE to the ER essential for successful infection." (PMID 32111841, 2020). "Indeed, we found that Stx18, an ER membrane SNARE essential in endosome-to-ER delivery of BK PyV16, binds to EMC4 and EMC7, and also plays an important role in sorting SV40 to the ER to promote infection." (PMID 32111841, 2020). "We measured effects on viral binding and uptake by quantifying the amount of viral RNA after virus incubation with WT and EMC4 KO cells at 2 and 6 hr post-infection (hpi), where we did not observe a difference." (PMID 31516121, 2019).
EMC4 also shares sentences with these, for which no sentence is quoted: abortion (1 paper); Alzheimer disease (1); cancer (1); Retinal dystrophy (1); synucleinopathies (1); tumours (1); ZIKV infection (1).